BCL2 (BCL2 apoptosis regulator)
Diseases named in the same sentence as BCL2 in open-access papers (continued):
Sharing a sentence is not in itself a finding about the gene and the disease.
ovarian carcinoma (continued). "Previous studies have shown that ALKBH5 inhibits Bcl2 degradation by reducing m6A modification, thereby regulating cell apoptosis in ovarian cancer, hepatocellular carcinoma, and cerebral ischemia-reperfusion injury." (PMID 35799597, 2022). "This work confirms the importance of Bcl-2 in ovarian cancer and validates its role as a key gene in mediating drug resistance via apoptotic suppression." (PMID 36551731, 2022). "Our results show that the decrease of Bcl-2 expression and the increase of Bax expression were significantly detected in ovarian cancer cells treated with the combination of olaparib and proguanil." (PMID 35165509, 2022). "On the other hand, the PARP inhibitors in combination with BCL2 inhibitors were observed to have a synergistic effect in the therapy of ovarian cancer." (PMID 35342397, 2022). "Only one potential gene target in this review, Bcl-2, is currently being evaluated in clinical trials for resistant ovarian cancer (NCT02591095)." (PMID 36551731, 2022). "Deletion of LINC00152 elevated cisplatin sensitivity via upregulation of Bax and cleaved caspase-3, and downregulation of Bcl-2 in ovarian cancer." (PMID 36105363, 2022). "Bcl-2 negative samples responded to chemotherapy, thus exemplifying the activity of Bcl-2 in promoting ovarian cancer cell survival." (PMID 36551731, 2022). "In ovarian cancer cells, the overexpression of Bcl-2 attenuated cisplatin cytotoxicity by downregulating ER-mitochondrial Ca2+ signal transduction." (PMID 35851420, 2022). "Caffeic acid phenethyl ester can control the balance between Bax/Bcl-2 and induce the apoptosis of the ovarian cancer OV7 cells to play an antitumor role." (PMID 34675987, 2021). "Six out of 20 genes (IFN-γ, Foxp3, IL-4, BCL-2, Oct4 and survivin) selected by the Laplacian score showed key roles in the development of ovarian cancer and their prognostic values were clinically and statistically confirmed." (PMID 34181334, 2021). "MA1-treated A2780S cells showed a different RNA profile than MA1-treated A2780CP, in which two of the genes (Bcl2 and Caspases9) showed different expression patterns in the sensitive ovarian cancer cells upon treatment." (PMID 34199287, 2021). "Recently, inhibition of Bcl2 in SKOV3 ovarian cancer cells, appeared to reverse the Warburg effect and promoted oxidative stress-induced apoptosis in vitro." (PMID 34386072, 2021). "In this study, both Survivin and Bcl-2 were significantly overexpressed in multi-drug resistant ovarian cancer cells." (PMID 33738259, 2021). "Under stress conditions, BCL2A1 accumulated and colocalized with mitochondria to suppress intrinsic cell apoptosis by interacting with the BH3-only subfamily BCL2 members HRK/BAD/BID in ovarian cancer cells." (PMID 34572804, 2021). "Downregulation of E2F4as also notably reduced levels of Bcl-2 and Bcl-xl, and elevated levels of Bax and Bim in ovarian cancer cells." (PMID 33287341, 2020). "Applying gain-of-function experiments, our data revealed that miR-454 overexpression suppressed the proliferation, migration and invasion of ovarian cancer cells, and promoted cell apoptosis by regulating the Bcl-2/Bax axis and Caspase cascade." (PMID 32536825, 2020). "In a study conducted on ovarian cancer cells, Tan IIA caused activation of caspase -3, -8, and -9 and decreased the expression of Bcl-2." (PMID 36046197, 2020). "The RBP ribonucleoprotein 1, translational regulator 1 (LARP1) promotes ovarian cancer progression and by altering the stability of its target mRNAs B cell lymphoma 2 (BCL2) and BCL-2–interacting killer (BIK)." (PMID 33193718, 2020).
ovarian carcinoma (continued). "Increasing the [BH3-only Bim, Puma, Noxa proapoptotic]/[Bcl-xL, Mcl-1 antiapoptotic] proteins ratio was proven to efficiently kill ovarian carcinoma cells and development of new molecules to imbalance Bcl-2 member equilibrium are strongly required." (PMID 32424251, 2020). "For example, in combination with cisplatin, TQ demonstrated an increased expression of the pro-apoptotic BAX and decreased anti-apoptotic BCL2 in a ovarian carcinoma (SKOV3) cell line." (PMID 32793594, 2020). "The study claims that metformin treatment in low glucose environment enhances ovarian cancer cell cytotoxicity by apoptosis induction via mitochondrial pathway, which was confirmed by the increased ratio of Bax/Bcl-2." (PMID 31534778, 2019). "MiR-509-3p has been reported to sensitize ovarian cancer cells to cisplatin treatment by targeting multiple anti-apoptosis genes including BCL2." (PMID 35582723, 2019). "Combined administration of both agents led to a strong synergistic cytotoxicity and apoptosis in human ovarian cancer cells and reduced among others Bcl-2 and inhibited both DNMT and histone deacetylase (HDAC) activities." (PMID 35582723, 2019). "miR-125b-5p serves as a novel biomarker for HBV-positive hepatocellular carcinoma, and miR-34b-5p inhibits the expression of Bcl-2 in ovarian cancer cells." (PMID 31485447, 2019). "Quercetin increased ER stress, inhibited STAT3 phophphorylation, downregulated Bcl-2 expression in ovarian cancer cells." (PMID 31202269, 2019). "H. diffusa Willd also obviously inhibited the cell proliferation and induced apoptosis by decreasing the expression of Bcl-2 and increasing the expressions of caspases-9 and -3 in ovarian cancer A2780 cells." (PMID 31354479, 2019). "Silencing LGR6 elevated the activity of caspase-3 and -9 but reduced the expression of Bcl-2 and Bcl-xL in ovarian cancer cells." (PMID 31193124, 2019). "Effects on S-phase arrest coupled to Bcl-2 downregulation has been shown earlier to have antiproliferative effect in ovarian cancer cells." (PMID 31263600, 2019). "This study confirms that ALKBH5 is a tumor-promoting gene in epithelial ovarian cancer, which is involved in the mTOR pathway and BCL-2-Beclin1 complex." (PMID 30987661, 2019). "The gene-specific m6A qPCR assays revealed that the levels of m6A+BCL-2 mRNA were increased in ovarian cancer SKOV3 cells infected with LVRU6P-01 or LVRU6P-01 as compared to that of SKOV3 cells infected with LVRU6P-NC." (PMID 30987661, 2019). "This indicates that the decrease in BCL9 expression inhibited ovarian cancer cell proliferation by promoting the apoptosis of ovarian cancer cells by increasing the BAX/BCL2 expression ratio." (PMID 31827404, 2019). "The BCL-2 mRNA F/V ratio was decreased in ovarian cancer SKOV3 cells infected with LVRU6P-01 or LVRU6P-02 as compared to that of SKOV3 cells infected with LVRU6P-NC." (PMID 30987661, 2019). "Recent study has demonstrated that Bcl-2 is overexpressed in ovarian cancer and has a significant positive correlation with sensitivity to cisplatin in ovarian cancer cells." (PMID 30454003, 2018). "Over-expression of Bcl-2 protein has been observed in side population cells from high grade ovarian cancer." (PMID 29914196, 2018).
ovarian carcinoma (continued). "In the current studies, we demonstrate that PLGA nanoparticles containing both MDR1 and BCL2 siRNA can efficiently suppress the function of both genes on the MDR ovarian cancer cells." (PMID 29760419, 2018). "MiR-34a-5p overexpression was confirmed to suppress ovarian cancer (OC) cell growth and induce apoptosis by directly targeting Bcl2." (PMID 29393891, 2018). "Based on the fact that Bcl-2 is an important anti-apoptotic protein protects ovarian cancer cells from TX and develop chemoresisitance." (PMID 30046387, 2018). "Bcl-2 has been reported to protect ovarian cancer cells from drug-induced apoptosis, contributing to chemo-resistance." (PMID 28086831, 2017). "CoQ0-induced elevated Beclin-1/Bcl-2 ratio and Bax/Bcl-2 ratio in ovarian cancer cells suggest that CoQ0 promotes cell death via pro-apoptotic signals." (PMID 28808311, 2017). "Compound 15k induced apoptosis in ovarian cancer cells in a time-dependent manner by significantly upregulating the expression of Bax and Bak and downregulating the expression of Bcl-2." (PMID 28824426, 2017). "Our findings suggest that E2F1 functions as an oncogene in ovarian carcinoma in part by upregulating Bcl-2, cyclin D1, survivin, MMP2, and MMP9 expression." (PMID 28146423, 2017). "This suggests that miR-519d has suppressive effects on ovarian carcinoma by downregulating RhoC, Bcl-2, cyclin D1, survivin, MMP2, MMP9, STAT3 and HuR expression." (PMID 28146423, 2017). "In ovarian cancer, ET-1 confers resistance to paclitaxel-induced apoptosis by a BCL-2-dependent mechanism that can be reversed by the addition of specific ETAR antagonist." (PMID 29163807, 2017). "Here we identified that lysine demethylase KDM3A as a critical regulator of ovarian cancer stemness and cisplatin resistance by inducing the expressions of pluripotent molecules Sox2 and Nanog and anti-apoptotic B-cell lymphoma 2 (Bcl-2), respectively." (PMID 27694900, 2017). "Silencing of ILK expression using shRNA in ovarian cancer cells suppressed anti-apoptotic bcl-2 and increased pro-apoptotic bax expression, leading to enhanced apoptosis." (PMID 26959113, 2016). "Over-expression of ARHI led to an accelerated level of autophagy by suppressing PI3K/AKT and reducing the expression of Bcl-2 in ovarian cancer cells." (PMID 27825125, 2016). "A combination of estrogen and progesterone decreases cell proliferation and inhibits the expression of Bcl-2 via let-7a and miR-34b in ovarian cancer cells." (PMID 26871282, 2016). "This is reinforced by the more frequent deregulation of Bcl-XL than Bcl-2 in ovarian cancer reported in the cancer genome atlas." (PMID 27080533, 2016). "Re-expression of NDN decreased Bcl-2 levels and induced apoptosis, which significantly inhibited ovarian cancer cell growth in cell culture and in xenografts." (PMID 26689988, 2016). "Inhibition of autophagy contributed to ovarian carcinoma development was required for suppression of Beclin1 and up-regulation of Bcl-2." (PMID 27825125, 2016). "Navitoclax, which has undergone clinical evaluation in several cancers, inhibits Bcl-2, Bcl-XL and Bcl-w and consequently it is likely to be effective in potentiating the activity of carboplatin in a larger proportion of ovarian cancer patients than ABT-199." (PMID 27080533, 2016). "Hajiahmadi and colleagues found that A2BAR agonist NECA can induce ovarian cancer cell apoptosis via Bax/Bcl-2 and caspase-3." (PMID 27008703, 2016). "We have previously shown that ABT-737 and navitoclax, BH3 mimetics which can inhibit both Bcl-2 and Bcl-XL, potentiate the activity of carboplatin in ovarian cancer cell lines." (PMID 27080533, 2016). "Terminal node 1 was defined as individuals carrying the homozygous variant genotypes (VV) for rs11152377 of BCL-2, following by the homozygous wildtype (WW) for rs2889 of TNFRSF10B, which had the lowest ovarian cancer risk as the reference node." (PMID 27462919, 2016).
ovarian carcinoma (continued). "A personalized medicine approach is likely to be necessary to use ABT-199 in ovarian cancer and measurement of Bcl-2 expression in patients’ tumours seems advisable, particularly in light of the antagonism we have observed in some cell lines." (PMID 27080533, 2016). "Ovarian cancer like many other tumors has been shown to overexpress the Bcl-2 and/or its family members." (PMID 25823945, 2015). "In the present study,we investigate the effect of TW-37 or / and in combination with cisplain on several ovarian cancer (OC) cell lines with high bcl-2 expression." (PMID 25823945, 2015). "Bcl-2 plays a major role in the pathobiology and drug resistance of ovarian cancer, and inhibition of bcl-2 was useful for OC therapy." (PMID 25823945, 2015). "The overexpression of miR-17-5p inhibited the ability of chemotherapy to increase BAX expression, while the Bcl-2 expression was increased in miR-17-5p overexpressed ovarian cancer cells." (PMID 26500892, 2015). "We found that the expression of anti-apoptotic protein Bcl-2 in ovarian cancer cells treated with PMBPs significantly decreased in a dose-dependent manner (p<0." (PMID 26539720, 2015). "In our previous study, we have confirmed that dasatinib can enhance paclitaxel sensitivity of ovarian cancer cells through p27Kip1-mediated suppression of Bcl-2 expression." (PMID 26146988, 2015). "Heparin coated Doxorubicin super-paramagnetic iron oxide nanoparticles promoted apoptosis due to regulation of anti-apoptotic genes including caspase-3, bax, bcl-2 and surviving in human ovarian cancer cell lines A2780." (PMID 25071577, 2014). "Expression of Bcl-2 is important in protection from drug-induced apoptosis in ovarian cancer thereby contributing to chemo-resistance." (PMID 24495391, 2014). "The relationship of the bcl-2 with the ovarian cancer progression stage was shown, with its usefulness in the early ovarian cancer detection as well as the prognosis of the disease course." (PMID 25018782, 2014). "On the other hand, high expression of BCL-2 inhibits not only autophagy but also apoptosis, thus influencing the cytotoxic response of ovarian cancer cells to chemotherapeutics." (PMID 25136588, 2014). "BECLIN 1 was initially isolated as an interactor of the oncogenic antiapoptotic protein BCL-2, and it was reported to be deleted in up to 75% of human ovarian cancers." (PMID 25136588, 2014). "We observed that parental ovarian cancer cells have undetectable level of Bcl-2 and exhibited phosphorylation of Bcl-XL after BPR0L075 exposure." (PMID 23762410, 2013). "Previous studies have shown that acquired cisplatin resistance in ovarian cancer is correlated with an increased expression of Bcl-2 and XIAP, which are regulated by NF-κB." (PMID 24137468, 2013). "In our research, we found that 53BP1 induced apoptosis of ovarian cancer cells by increasing pro-apoptotic Bax expression and decreasing anti-apoptotic Bcl-2 expression, leading to up-regulation of the ratio of Bax/Bcl-2." (PMID 22266878, 2012). "In vitro metformin has also been demonstrated to induce apoptosis in human ovarian cancer cell lines by directly activating caspases 3/7, downregulating Bcl-2 and Bcl-xl expression, whereas upregulating Bax and Bad expression." (PMID 22421948, 2012). "It was previously shown that urinary Bcl-2 levels are reliably elevated during early and late stages of ovarian cancer." (PMID 22969352, 2012). "B-cell lymphoma 2 protein (Bcl-2) found in urine is under investigation as a biomarker for non-invasive early detection of ovarian cancer." (PMID 23112714, 2012). "It was previously shown that urinary Bcl-2 levels are elevated during different stages of ovarian cancer." (PMID 22969352, 2012).
ovarian carcinoma (continued). "In initial experiments, it was observed that Bcl-2 concentrations were detectable in the range relevant to ovarian cancer, even from a protein mixture." (PMID 23112714, 2012). "The efficacy of Bcl-2 as a biomarker for ovarian cancer was further validated by comparison to CA125 serum levels using ELISA tests on 35 samples from the same cohort." (PMID 22969352, 2012). "The diagnostic relevance of this surface was demonstrated by its ability to detect levels of Bcl-2 comparable to those found in early stage ovarian cancer patients." (PMID 23112714, 2012). "Our prior studies demonstrate that after ovarian carcinoma cells adhere with fibronectin (FN), Bcl-2 expression is increased, and the FN-RMG-1-H group is higher than the FN-RMG-1 group." (PMID 23443083, 2012). "The target sensitivity for diagnosis and identifying the stage of ovarian cancer was successfully achieved with demonstrated Bcl-2 detection capability of 500 pg/mL." (PMID 22969352, 2012). "The average urinary level of Bcl-2 was found to be 0.59 ng/mL in healthy controls, 1.12 ng/mL in benign disorders, 2.60 ng/mL in early-stage ovarian cancer and 3.58 ng/mL in late-stage ovarian cancer." (PMID 22969352, 2012). "The mode of action in SKOV-3 ovarian cancer cells relies on the generation of ROS, caspase activation, Bcl-2 reduction, DNA degradation and G2/M phase cell cycle block." (PMID 20184758, 2010). "The capacity to target NF-κB, STAT5, and Bcl-2/Bcl-xL pathways simultaneously, and thus maximize the suppression of Bcl-xL expression, should be of great benefit to ovarian cancer patients who have developed carboplatin resistance." (PMID 20585448, 2010). "Bcl-2 itself has in vitro an anti-apoptotic activity and has been inversely correlated with the level of apoptotic index in ovarian cancer tissues." (PMID 24281100, 2010). "Previous reports have shown that the anti-apoptotic protein Bcl-2 is overexpressed in many solid neoplasms, including ovarian cancers, and contributes to neoplastic transformation and drug-resistant disease, resulting in poor clinical outcome." (PMID 19852858, 2009). "Further, 65% (11/17) benign specimens showed epithelial Bcl-2 staining in more than 50% of their epithelial cells, whereas, 18% (2/11) and 29% (8/28) normal and ovarian cancer tissues, respectively, displayed epithelial Bcl-2 staining to the same extent." (PMID 19852858, 2009). "Specifically, Bcl-2, recognized as the prototypical anti-apoptotic protein, is overexpressed in a number of solid tumors, including ovarian cancer, and contributes to neoplastic transformation through inhibition of apoptosis, thereby promoting tumor survival." (PMID 19852858, 2009).